PRNP (prion protein (Kanno blood group))
Diseases named in the same sentence as PRNP in open-access papers (continued):
Sharing a sentence is not in itself a finding about the gene and the disease.
prion disease (continued). "Furthermore, the prion protein (PRNP), traditionally linked with prion diseases, also has functions in cellular processes such as signal transduction, cell adhesion, and protection against oxidative stress." (PMID 39926598, 2024). "This single-center longitudinal cohort study has followed known carriers of PRNP pathogenic variants at risk for prion disease, individuals with a close relative who died of genetic prion disease but who have not undergone predictive genetic testing, and controls." (PMID 38896810, 2024). "Thus, preventing or delaying prion disease onset has been suggested as one of the most promising goals in carriers of pathogenic mutations in the PRNP gene." (PMID 39200190, 2024). "Moreover, it was reported that somatic mutation of humans’ PRNP was predicted to be one of the factors responsible for prion disease." (PMID 38355406, 2024). "Lastly, Sonia Vallabh is a PRNP mutation carrier, and in the face of incurable diseases, she did not wait for fate but took a proactive stance in innovative clinical trials for genetic prion diseases." (PMID 38500676, 2024). "Our study serves as the first to simultaneously investigate the polymorphism of PRNP gene in Nigerian livestock species and provides relevant information that could be adopted in programs targeted at breeding for prion diseases resistance." (PMID 38355406, 2024). "Modelling sporadic, or more precisely, spontaneous idiopathic prion diseases in animal models has been attempted through introduction of PRNP mutations associated with human genetic prion diseases, potentially able to increase the proneness of spontaneous misfolding." (PMID 37679832, 2023). "In terms of the role epigenetics might play in understanding causal mechanisms and the pathogenesis of prion disease, we await with great interest the development of strategies to manipulate PRNP expression in patients and those at-risk of prion diseases." (PMID 35307791, 2023). "A small percentage (10–15%) of prion diseases may be related to genetic mutations in the prion gene (PRNP)." (PMID 36614069, 2022). "PRNP mutations account for 10–15% of all human prion diseases." (PMID 35885064, 2022). "However, all prion diseases are also affected by PRNP polymorphisms, with the polymorphic codon 129 having the strongest influence across all prion diseases." (PMID 36277922, 2022). "The somatic mutations in the PRNP gene may lead to human prion diseases with fatal and irreversible spongiform generation and astrocytosis in brain lesions." (PMID 35371305, 2022). "A RVD PRNP was found which could cause a rare but slow-acting variant of prion disease that is specifically characteristic for certain genetic mutations." (PMID 35752680, 2022). "In addition to these disease-related mutations, single nucleotide polymorphisms at codons 129 and 219 of the PRNP gene represent susceptibility factors for human prion diseases." (PMID 35493823, 2022). "In prion diseases, somatic mutation of PRNP’s OPR has been hypothesised as a possible cause of sporadic CJD14,15." (PMID 35585119, 2022). "We also found a variant in the gene PRNP, which is associated with familial forms of prion disease." (PMID 35650585, 2022). "PRNP gene sequencing is the primary diagnostic technique in genetic prion disease." (PMID 35454316, 2022). "Beyond PRNP, we also detected 23 significant single-nucleotide polymorphisms (P-value ≤ 5E-05) implicating ≥24 positional candidate genes; many of which have been directly implicated in Parkinson’s, Alzheimer’s and prion diseases." (PMID 35536181, 2022). "The strongest determinant of susceptibility to prion diseases is the host PRNP sequence." (PMID 35318913, 2022). "Finally, we explored somatic mosaicism of PRNP’s octapeptide repeat region, which is a hypothetical cause of sporadic prion disease." (PMID 35585119, 2022).
prion disease (continued). "The pathogenesis of prion diseases relies on the templated seeded conversion of the cellular prion protein (PrPC), encoded by the prion protein (PRNP) gene, into a pathological isoform with abnormal conformation (PrPSc), which shows a tendency to aggregate and forms amyloid fibrils." (PMID 33776643, 2021). "Familial CJD is an inherited form of prion disease caused by mutations in the PRNP gene." (PMID 34960722, 2021). "Because of the direct link between PrPC and TSEs, a host’s PRNP genotype and the primary structure of the PrPC protein(s) encoded have been shown to contribute to varying degrees of susceptibility to species-specific prion diseases, in some cases completely preventing infection." (PMID 34573378, 2021). "Polymorphisms in cervid Prnp have been identified at codon 132 of the elk Prnp gene, encoding either methionine (M) or leucine (L), equivalent to that of position 129 (M/Valine) in the human PRNP gene, which has significant effects on human prion disease presentation and susceptibility." (PMID 34310662, 2021). "Since the genetic polymorphisms of the cat PRNP gene can be associated with susceptibility to prion disease, identification and functional analysis of polymorphisms of the PRNP gene in large samples of healthy cats are an essential baseline study to identify potential FSE-related genetic factor." (PMID 33374431, 2020). "Meanwhile, individuals at risk for genetic prion disease, caused by protein-altering variants in the prion protein gene (PRNP), can be identified through predictive genetic testing when disease onset is on expectation years or decades away, ahead of molecular markers of pathology." (PMID 32776089, 2020). "Some prion diseases can be inherited, and are linked to specific mutations in the PRNP gene that appear to predispose the individuals that carry these mutations to prion diseases such as Gerstmann–Sträussler–Scheinker disease (GSS) and fatal familial insomnia." (PMID 33023255, 2020). "In the inherited forms of prion diseases, genetic mutations in the PRNP gene may induce conformational changes, but the process of conformational alteration has not been completely understood." (PMID 32992764, 2020). "Thus, we investigated the genetic polymorphisms of the cat PRNP gene and analyzed the structural characteristics of the PrP of cats compared to those of dog, prion disease-resistant animal." (PMID 33374431, 2020). "Prion disease can be caused by either infectious proteins or mutations to the PRNP gene in humans." (PMID 31037649, 2019). "Prion diseases are zoonotic diseases with a broad infection spectrum among mammalian hosts and are caused by the misfolded prion protein (PrPSc) derived from the normal prion protein (PrPC), which encodes the prion protein gene (PRNP)." (PMID 31795947, 2019). "Finally, we found significant differences in the number of PRNP SNPs between prion disease-susceptible species and prion disease-resistant species." (PMID 31795947, 2019). "In addition, there are multiple examples of PRNP polymorphisms that influence prion disease susceptibility in other mammals." (PMID 31717531, 2019). "In addition, dog, which is known as prion disease resistant animal, showed very little polymorphisms in the PRNP ORF." (PMID 31795947, 2019). "Of note, an important clinical trial was recently started for preventive purposes, enrolling still asymptomatic subjects that are at risk of developing a rare form of prion disease, fatal familial insomnia, since they bear a high-penetrance mutation of the PRNP gene." (PMID 30791416, 2019). "For sCJD, the heterozygous state M129V appears to be protective against the disease, whereas the homozygous M129M and V129V genotypes carry increased risk for all forms of prion diseases suggesting that the genotype of PRNP at codon 129 influences the susceptibility and the phenotype of the sCJD." (PMID 27793473, 2017).
prion disease (continued). "Indeed, the need to define allele-specific estimates of disease penetrance is an important concept, as recently illustrated for prion disease in which the disease-penetrance of individual PRNP variants ranged from <0.1% to ~100%." (PMID 29308445, 2017). "Prion diseases are also rare causes of neuropsychiatric deterioration that can occur sporadically without an identifiable cause, or can be attributed to mutations in the PRNP gene." (PMID 24555712, 2014). "Human prion diseases usually occur sporadically, or very rarely through infectious transmission, but can also arise (in 5–15% of cases) in association with phenotypically dominant mutations in the autosomal gene (PRNP) that encodes the prion glycoprotein PrP." (PMID 24555712, 2014). "Molecular strain typing of human prion diseases has focused mainly on differences in the PrPres size and glycosylation site occupancy in conjunction with the presence of mutations and polymorphisms in the prion protein gene (PRNP)." (PMID 24063733, 2013). "Prion diseases may be caused by prion exposure (acquired forms), mutations in PRNP gene (genetic or hereditary forms) and sporadic events in which the source of infection has not yet been demonstrated (idiopathic or sporadic forms)." (PMID 25437201, 2013). "Increasing evidence suggests that other genes in addition to the PRNP genes also contribute to the genetic susceptibility of acquired TSEs, thus there is a need to improve our understanding of the molecular mechanisms underlying prion disease pathogenesis." (PMID 23372423, 2012). "Within species, sequence variants of PRNP may give the prospective host a different risk of succumbing to prion diseases." (PMID 23236380, 2012). "On the other hand, mutations in the normal prion protein encoded by the PRioN Protein (PRNP) gene, are linked to genetically inherited prion diseases including Gerstmann-Strausler-Sheinker (GSS) disease, fatal familial insomnia (FFI) and genetically associated CJD." (PMID 23372423, 2012). "Analysing the molecular and population genetics of PRNP should enable a genetically-based assessment of the risk for carnivores that may become or already are exposed to prion diseases." (PMID 23236380, 2012). "Moreover, mutations in the human PRNP gene are linked to over 30 inherited forms of human prion diseases." (PMID 23071594, 2012). "The clinical presentation of human prion disease varies enormously and there is considerable overlap observed between individuals with different disease aetiologies and even in family members with the same pathogenic PRNP mutation." (PMID 20880036, 2010). "In inherited human prion diseases, mutations in the open reading frame of the PrP gene (PRNP) are hypothesized to favor spontaneous generation of PrPSc in specific brain regions leading to neuronal cell degeneration and death." (PMID 20661422, 2010). "One of the strongest arguments supporting the “protein-only hypothesis” is the link between inherited prion diseases and mutations in the PRNP gene." (PMID 20661422, 2010). "PRNP plays an important role in conferring susceptibility or resistance to prion disease." (PMID 19351416, 2009). "The polymorphic codon 129 of PRNP was the main genetic risk factor for vCJD; however, additional candidate loci have been identified, which justifies functional analyses of these biological pathways in prion disease." (PMID 19081515, 2009). "Human and animal prion diseases are under genetic control, but apart from PRNP (the gene that encodes the prion protein), we understand little about human susceptibility to bovine spongiform encephalopathy (BSE) prions, the causal agent of variant Creutzfeldt–Jakob disease (vCJD)." (PMID 19081515, 2009). "Polymorphisms in the PRNP promoter region may be associated with increased susceptibility of prion diseases in cattle and mice." (PMID 19351416, 2009).
prion disease (continued). "However, a transgenic mouse expressing a bovine PRNP gene encoding 4 additional repeats did in fact develop a spontaneous prion disease." (PMID 18808703, 2008). "Mutations in the PRNP gene account for ~15% of all prion disease cases." (PMID 18366654, 2008). "PrPC, encoded by the PRNP gene, is a cell-surface neuronal and glial protein more commonly known for its ability to misfold into infectious and pathological protein aggregates that underlie prion diseases in humans and animals such as Creutzfeldt-Jakob disease, scrapie, and chronic wasting disease." (PMID 39264912, 2024). "Prion diseases (PrD) are a group of disorders characterized by the presence of aberrantly shaped proteins, called prions (proteinaceous infectious particles) encoded by the PRNP gene, that cause the accumulation of misfolded aggregated proteins in the central nervous system." (PMID 37274187, 2023). "Thus, we illustrate the utility of harnessing multiple lines of prion disease–specific evidence in the evaluation of the T201S variant, which may be similarly applied to assess other novel variants in PRNP." (PMID 29861043, 2018). "Moreover, the incubation period could also be modified in TSE due to the species barrier, which is modulated by specific polymorphisms of the PRNP gene and plays a key role in susceptibility to prion disease in other species such as sheep, and goats." (PMID 26742788, 2016). "Intracerebral inoculations of prions in transgenic mice expressing different PRNP polymorphic variants are highly valuable to point to a specific amino acid substitution as the unique mutation responsible for the resistance/susceptibility of a species to a prion disease." (PMID 27659200, 2016). "To then assess whether the physical properties of anchorless prions in mice applied to natural disease, we measured the chaotrope stability of anchorless prions from the brain of a patient with a rare familial prion disease due to a PRNP mutation coding for Q227X." (PMID 23637596, 2013). "Thus, polymorphisms in the coding region of PRNP might influence other neurodegenerative disorders in addition to prion diseases." (PMID 19351416, 2009). "Thus, in the light of the direct relationship between PrP amino acid sequence and susceptibility to prion disease, the aim of this paper is to increase the knowledge on mammalian PRNP sequences and to delve into their variability and the potential effects of TSEs on PRNP evolution." (PMID 40561181, 2025). "For this reason, we studied the PRNP gene from a phylogenetic perspective, potentially unveiling evolutionary events related to prion diseases." (PMID 40561181, 2025). "Conversely, prion diseases demonstrate catastrophic protein-level dysregulation, wherein the conformational misfolding of PRNP-encoded PrPc into β-sheet-rich PrPSc initiates self-propagating neurotoxicity." (PMID 40563902, 2025). "In transgenic mice in which the PRNP gene was knocked out during the early stage of prion disease, a reversal of early spongiform changes was observed." (PMID 40076721, 2025). "Mutations within exon 3 of the PRNP gene or the pathological conversion of natively folded PrPC into its misfolded and infectious prion form (PrPSc) lead to progressive, fatal neurodegenerative prion diseases." (PMID 41340001, 2025). "It has been reported that the resistance to scrapie is intently regulated by SNPs of the PRNP gene and controlled by the prion disease agent, and the distribution of SNPs at the ORF of PRNP gene in various species was presented." (PMID 38355406, 2024). "Beyond the potential in treating prion disease, therapeutic targeting of PRNP will also provide practical experience on the benefits and unforeseen challenges of broader clinical applications of CHARM." (PMID 38935715, 2024). "Genetic prion diseases (gCJD, GSS, and FFI) are attributed to mutations in the PRNP gene, constituting ~15% of all human prion diseases." (PMID 38500676, 2024).
prion disease (continued). "Although there are three types of prion diseases (sporadic, genetic, and acquired), all forms are affected by PRNP as the production of PrPc is necessary for disease." (PMID 36277922, 2022). "PRNP genotyping in prion diseases cases is routinely performed using both Sanger sequencing and gel electrophoresis of the protein-coding region." (PMID 35585119, 2022). "Rapid and accurate sequencing of the prion gene PRNP is paramount to human prion disease diagnosis and for animal surveillance programmes." (PMID 35585119, 2022). "Sequencing of PRNP is of crucial importance in informing patients, veterinaries, and clinicians about prion diseases diagnosis and management." (PMID 35585119, 2022). "Here, we used long-range PCR and Nanopore sequencing to sequence the full length of PRNP, including its regulatory region, in 25 samples from blood and brain of individuals with inherited or sporadic prion diseases." (PMID 35585119, 2022). "DWI sequences were available for 104 of these patients, including four patients who were later diagnosed with inherited prion disease (2 E200K, 2 P102L) following PRNP sequencing, whose clinical picture at the time of referral was indistinguishable from sCJD." (PMID 35362733, 2022). "PRNP sequencing is therefore an important biomarker that should be considered in the differential diagnosis of prion diseases and is crucial in cases of atypical, rapidly progressive dementias." (PMID 35885064, 2022). "In contrast to animal prion diseases, the human prion disease includes genetic forms linked to mutations in the PRNP gene encoding for PrPC." (PMID 34324063, 2021). "In this study, we focused on PRNP mutations linked to CJD or FFI, representing only a subset of the inherited prion diseases, albeit the most common." (PMID 34324063, 2021). "This will bring new knowledge on ovine prion diseases that are under strong genetic control of the prion PRNP gene." (PMID 33941270, 2021). "Prion disease biomarker tests developed in the last two decades allow the detection of symptomatic sCJD and genetic prion disease cases, with PRNP sequence variations mimicking the sporadic phenotype (e.g., PRNP-E200K and PRNP-V210I) with high accuracy." (PMID 32059611, 2020). "The mean incubation time until clinical signs of prion disease was 601 days post-inoculation (dpi) in PRNP+/+ goats and 773 dpi in PRNP+/Ter goats." (PMID 31924264, 2020). "The mean incubation period until clinical signs of prion disease was 601 dpi (SD = 14) in the PRNP+/+ goats." (PMID 31924264, 2020). "It was promising that the top scoring pathway was related to the development of prion diseases, with 3 out of the 21 miRNA signature (miR-148a-3p, miR-186-5p, miR-30e-3p) directly targeting the PRNP gene." (PMID 31873177, 2019). "To study the influence of the PRNP codon 129 MV polymorphism on MDH1-levels in CSF, we stratified our genetic prion disease cohort according to the PRNP codon 129 genotype in gCJD (E200K MM and MV, V210I MM and MV, as well as FFI-D178N MM and MV)." (PMID 31795176, 2019). "Familial or genetic prion diseases constitute approximately 10% of human prion diseases and are associated with a range of dominantly inherited mutations within the open reading frame (ORF) of the prion protein gene (PRNP)." (PMID 28851967, 2017). "Although case numbers remain low, the prevalence of this novel prion disease appears to vary according to the codon 129 genotype of affected persons: 62% of reported cases have been detected in persons of the PRNP codon 129VV genotype." (PMID 25418327, 2014). "Variably protease-sensitive prionopathy (VPSPr) can occur in persons of all codon 129 genotypes in the human prion protein gene (PRNP) and is characterized by a unique biochemical profile when compared with other human prion diseases." (PMID 25418327, 2014). "All 11 patients were of the PRNP codon 129VV genotype, and postmortem examination of brain tissues showed that the patients had a spongiform encephalopathy." (PMID 25418327, 2014).